JAG1 (jagged canonical Notch ligand 1)
Diseases named in the same sentence as JAG1 in open-access papers (continued):
Sharing a sentence is not in itself a finding about the gene and the disease.
infection (16 papers, 2009 to 2025). The state of being infected such as from the introduction of a foreign agent such as serum, vaccine, antigenic substance or organism. "Consistent with this, our previous studies and others have shown that treatment of mouse cochleas with a Wnt activator, or infection of chicken cochleas with a Wnt-ligand-expressing virus showed an increase in Jag1, or the chicken homologue, Serrate1." (PMID 39254648, 2024). "The expression of the Jag1 gene was also increased compared to the control at all stages of infection." (PMID 36355906, 2022). "Twenty-four hours after TLR activation through in vitro infection or LPS stimulation, the expression of JAG1 decreases, whereas DLL1 gene expression is highly induced and translated into the protein DLL1." (PMID 30042932, 2018). "Therefore, downregulation of JAG-1 was induced in the cells at day 6 and 12 of otic progenitor differentiation (designated as J1-6d and J1-12d infection schemes, respectively)." (PMID 34940631, 2021). "The expression of otic progenitor-specific genes and proteins in the J1-6d infection scheme was significantly lower than that of the control cells, which supported the previous statement “JAG-1 could stabilize prosensory fate”." (PMID 34940631, 2021). "Therefore, our findings support the concept that the IFN-γ-JAG1 axis is involved in the EC instruction of the antimicrobial MΦ response against M. leprae at the site of infection." (PMID 27532668, 2016). "The periodic expression of DLL4 during lytic infection may contribute to “topping up” Notch signaling established by JAG1 during latency." (PMID 19816565, 2009). "The use of 25 to 100 mg/kg of baicalin upregulated Notch 1, RBP-J, JAG1, and HES1 mRNA expression levels from the blood vessels compared to the infection group (p < 0.01)." (PMID 40427615, 2025). "vFLIP increased JAG1 protein expression in LEC as measured by western blotting and increased JAG1 was also observed in the spindle-shaped cells characteristic of vFLIP infection." (PMID 19816565, 2009). "Therefore, JAG-1-shRNA2, JAG-2-shRNA4, and DLL-1-shRNA3 vectors were chosen for subsequent stable infection." (PMID 34940631, 2021). "We have previously shown that Jag1 and NICD1 protein levels did not decrease before 16-24hpi, which was after Hes1 downregulation started (12hpi), indicating the Hes1 downregulation is not a consequence of Jag1 and NICD1 dysregulation in the IE phase of infection." (PMID 28750047, 2017).
genetic disorder (10 papers, 2009 to 2024). "ALGS is a rare genetic disorder characterized by liver, heart, eye, and skeletal abnormalities due to mutations in JAG1 or NOTCH2 genes." (PMID 39175640, 2024). "RBS is due to the mutations in the ESCO2 gene that also regulates cohesin, whereas AGS is an independent genetic disorder due primarily to mutations in the JAG1 gene, a member of the Notch signaling pathway." (PMID 19468298, 2009).
adenocarcinoma (6 papers, 2015 to 2023). A common cancer characterized by the presence of malignant glandular cells. "JAG1 expression was tied to a better OS in low differentiation adenocarcinoma, HR 0.59 (0.38–0.91), p = 0.017 and high differentiation adenocarcinoma, HR 0.18 (0.04–0.79), p = 0.011." (PMID 36071128, 2022).
kidney disease (5 papers, 2018 to 2025). "The two causative genes JAG1 and NOTCH2 are expressed during kidney development, can be reactivated during adulthood kidney disease, and Notch signalling is essential for vascular morphogenesis and remodelling in mice." (PMID 39446153, 2025).
cardiovascular disease (2 papers, 2023 to 2025). "In vascular endothelial cells, low JAG1 expression has been associated with cellular senescence, leading to cardiovascular diseases." (PMID 39796164, 2025).
peripheral neuropathy (2 papers, 2021 to 2024). A disorder affecting the peripheral nervous system. "The link between mutations in Jag1 and peripheral neuropathies also highlights an interesting avenue of clinically significant research to pursue in the future." (PMID 33722254, 2021). "Mutations in Jag1 have been associated with peripheral neuropathy in humans." (PMID 33722254, 2021). "There is increasing evidence of the importance of Notch signaling through its ligand Jag1 in the context of the peripheral nerve disorders." (PMID 33722254, 2021).
immunity disorders (1 paper, 2017). "The positive GPCs are small scaled but are interesting that JAG1 known to the biliary embryonic development and the other 3 genes known to immunity disorders are enlisted, which indicate the possible existence of disease heterogeneity." (PMID 28416017, 2017).
JAG1 also shares sentences with these, for which no sentence is quoted: multiple myeloma (9 papers); Myocardial fibrosis (7); asthma (5); proliferative retinopathy (5); cholangiocarcinoma (4); clear cell renal cell carcinoma (4); hemangioma (4); Barrett esophagus (3); chronic kidney disease (3); diabetic retinopathy (3); esophageal cancer (3); ovarian tumor (3); pulmonary hypertension (3); renal cell carcinoma (3); Type 2 Diabetes (3); Ureteral obstruction (3); acute lymphoblastic leukemia (2); acute promyelocytic leukemia (2); allergic asthma (2); autosomal dominant disease (2); CADASIL (2); cardiac disease (2); cognitive decline (2); diabetic macular edema (2); experimental autoimmune encephalomyelitis (2); glomerulosclerosis (2); Granuloma (2); Hyperglycemia (2); injury (2); Intellectual disability (2).
A further 159 diseases each share a sentence with JAG1 in 2 papers or fewer.